NLRP3 (NLR family pyrin domain containing 3)
Diseases named in the same sentence as NLRP3 in open-access papers (continued):
Sharing a sentence is not in itself a finding about the gene and the disease.
renal fibrosis (continued). "The results demonstrated that SMM could decrease the level of UA, improve kidney function and protect against renal fibrosis by inhibiting EMT and activation of NLRP3 inflammasome in tubular epithelial cells of chronic HN mice model induced by PO." (PMID 36271349, 2022). "NLRP3 inflammasome and Smad crosstalk to lead to EMT in renal fibrosis context." (PMID 32508821, 2020). "NLRP3 also has inflammasome-independent effects in tubular epithelial cells, including participating in SMAD2 and SMAD3 phosphorylation in response to TGFβ signaling, triggering renal fibrosis." (PMID 32521623, 2020). "The typical NLRP3/ASC/caspase-1/IL-1β/IL-18 axis promotes the pathophysiology of various kidney diseases by mediating inflammation, and this is likely a critical priming mechanism for renal fibrosis." (PMID 32039201, 2019). "Compared to infected WT mice, no reduction in Leptospira-induced fibrosis was observed in kidneys of either Nod1/2dko or Casp1ko mice, showing that Nod1, Nod2 and NLRP3 are not involved in the Leptospira-induced renal fibrosis." (PMID 24498450, 2014). "Furthermore, we demonstrated that renal fibrosis was attenuated by decreasing mitochondrial ROS and NLRP3 inflammasome production and TGFβ1 activation with MitoTEMPO, a selective mitochondrial-targeted antioxidant, and MCC950, a specific NLRP3 inhibitor." (PMID 36928344, 2023). "In addition, SMAD2 and SMAD3 knockout augmented the production of inflammatory factor (TNFα and IL-6), while SIRT2-mediated NLRP3 deacetylation protects against inflammation, indicating SIRT2 may be a more attractive target to improving renal fibrosis." (PMID 37777567, 2023). "Moreover, NLRP3 has inflammasome-independent (noncanonical) effects leading to renal fibrosis in DN." (PMID 35719709, 2022). "Previous studies have shown that high glucose level significantly induces the expression of pyroptosis markers, including NLRP3, caspase-1, pro-caspase-1, IL-1β, and pro-IL-1β, in GMCs, whereas inhibiting NLRP3 with MCC950 suppresses NLRP3/caspase-1/IL-1β activation and decreases renal fibrosis." (PMID 36204129, 2022). "Furthermore, a similar outcome was achieved by treatment with a specific small molecule NLRP3 inflammasome inhibitor (MCC950; detailed below in Section 6.1) that blocked NLRP3 activation in kidney DC, reduced IL-1β and IL-18 production and inhibited the progression of renal fibrosis." (PMID 31018590, 2019). "However, hematopoietic NLRP3 KO did not reverse UUO-induced renal fibrosis." (PMID 31694192, 2019). "Functionally, we unexpectedly found that NLRP3 is profibrotic, as mice lacking NLRP3 or macrophage-specific deletion of NLRP3 were protected from UUO and ischemia reperfusion injury (IRI)-induced renal fibrosis." (PMID 42157945, 2026). "The mitochondrial regulation in the absence of NLRP3 increases autophagy and attenuates apoptosis after UUO, which in turn prevents the progression of renal fibrosis." (PMID 36105212, 2022). "Notably, recent research found that ER stress is involved in angiotensin II-induced NLRP3 inflammasome activation, and pretreatment with 4-PBA could reduce the expression of both NLRP3 and inflammatory cytokines, suggesting that 4-PBA serves as a potential agent to reduce renal fibrosis." (PMID 34445377, 2021).
melanoma (138 papers, 2012 to 2025). A malignant, usually aggressive tumor composed of atypical, neoplastic melanocytes. "Constitutive activation of the NLRP3 inflammasome causes late-stage human melanoma cells to spontaneously secrete IL-1β via Caspase 1 processing." (PMID 39201564, 2024). "In a study of melanoma cell lines, the investigators found that inhibiting NLRP3 using OLT1177, caused suppression of IL-1β mediated inflammation by disrupting the IL-1β/IL-6/STAT3 axis." (PMID 39516433, 2024). "Conversely, a reduction or downregulation in several components of the NLRP3 inflammasome has been implicated in the pathogenesis of hepatocellular carcinoma, chemically induced squamous cell carcinoma, primary melanoma, and colitis-associated cancer." (PMID 38473997, 2024). "Melanoma patients with an NLRP3 mutation were found to exhibit increased infiltration of immune response cells, which was associated with better clinical efficacy." (PMID 38062129, 2024). "Apart from autoinflammatory diseases, where the significance of polymorphisms is well documented, in a similar way, it was shown that NLRP3 polymorphisms can be linked to cancer, namely colorectal cancer, melanoma, pancreatic cancer, and gastric cancer." (PMID 38397043, 2024). "Further, NLRP3 and IL-1β have been shown to be overexpressed in melanoma samples, and targeting tumor-associated NLRP3 prevents melanoma growth by reducing the expansion of myeloid-derived suppressor cells (MDSCs)." (PMID 39769450, 2024). "Genetic variations in the gene encoding the NLRP3 inflammasome pathway have been found to be linked to the occurrence of malignant tumors, including chronic myeloid leukemia and melanoma." (PMID 39201564, 2024). "In a previous study, after vaccination with dendritic cells, the survival of bearing melanoma xenograft NLRP3‐deficient mice was significantly prolonged due to the reduced number of MDSCs." (PMID 38116060, 2023). "Loss of NLRP3 in mice also increased the survival of mice against melanoma upon vaccination with a dendritic cell vaccine against melanoma cell line B16-F10 by about fourfold relative to control mice." (PMID 36669831, 2023). "Some previous studies in melanoma cell proliferation regulation indicated that NLRP3 was associated with the IL-1β secretion and T cell response suppression in the TME." (PMID 36276158, 2022). "Specific small nucleotide polymorphisms (SNPs) of NLRP3 have been identified in the genome of patients and associated with the development and/or prognosis of certain malignancies, including melanoma and colorectal cancer." (PMID 34638239, 2021). "Herein, we utilized publicly genomic data of 750 melanoma patients to explore the association of NLRP3 mutations with immunologic and genomic features." (PMID 34747716, 2021). "Subsequent to NLRP3 activation in melanoma cells, IL-1β induces melanoma-associated inflammation, resulting in immunosuppression." (PMID 33649199, 2021). "Here, we demonstrate that nucleotide-binding domain, leucine-rich containing family, pyrin domain-containing-3 (NLRP3) inflammasome activation in melanoma is linked to IL-1β production, inflammation, and immunosuppression." (PMID 33649199, 2021). "In this work, we also evaluated the markedly positive association of NLRP3 and IL-1β expression in melanoma and further confirmed the collective roles of both regulators." (PMID 34747716, 2021). "Collectively, the activated immune microenvironment was enriched in melanoma patients with NLRP3 mutations." (PMID 34747716, 2021). "Nevertheless, immunologic and immunotherapy implications of NLRP3 mutations in melanoma were obscure." (PMID 34747716, 2021). "Following NF-ĸB inhibition, NLRP3 inflammasome is inhibited, causing inactivation of caspase-1 and inhibition of IL-1 and IL-18 in melanoma cells." (PMID 33540625, 2021).
melanoma (continued). "By integrating and analyzing available genomic and clinical data of melanoma, NLRP3 mutations were identified to be associated with higher mutation and neoantigen burden, favorable microenvironment, and better tumor genomic features." (PMID 34747716, 2021). "Polymorphisms of NLRP3 are associated with the development of melanoma, and IL-1R-/- and caspase 1-/- mice rarely develop skin cancer after stimulation with chemical agents." (PMID 34064909, 2021). "Constitutive NLRP3 expression exists in several melanoma cells lines, and NLRP3 polymorphisms increase the risk to develop melanoma." (PMID 33649199, 2021). "The survival rate of mice with NLRP3 deficient bearing melanoma cell line B16F10 based on dendritic cell vaccination was significantly higher than that of their respective control groups." (PMID 33776057, 2021). "Wild-type macrophages stimulated with ATP enhanced the metastatic potential of melanoma cells; however, NLRP3- or caspase-1-deficient macrophages lost the ability to promote metastasis of melanoma cells." (PMID 33534121, 2021). "There is now data suggesting that NLRP3 inflammasome polymorphisms are related to different malignancies such as colon cancer and melanoma." (PMID 30447690, 2018). "NLRP3 inflammasome pathway failure has been linked to a variety of inflammation-induced disorders, and genetic variation in the NLRP3 inflammasome pathway gene has been linked to the development of malignant tumors such as chronic myeloid leukemia and melanoma." (PMID 37715239, 2023). "In melanoma, the mutational burden of the NLRP3 gene could provide useful data about the response to immunotherapy." (PMID 35804922, 2022). "This is in agreement with several studies, demonstrating that NLRP3 activation promoted tumor development in experimental models and is associated with susceptibility to melanoma and with poor survival in patients with advanced colorectal cancer or development of various hematologic malignancies." (PMID 36032139, 2022). "Another study has reported that modified gain-of-function variants of inflammasome genes NLRP1 and NLRP3 could increase patients’ risk for developing a sporadic malignant melanoma." (PMID 35334544, 2022). "Furthermore, melanoma tumour growth is linked to the ATP-regulated K+ channel P2 × 7 activity associated with NLRP3-inflammasome stimulation." (PMID 35334544, 2022). "However, consistent with the present data, loss of NLRP3 in melanoma increased antitumoral response and reduced metastasis (29, 48, –50)." (PMID 33649199, 2021). "Findings derived from our study suggest that NLRP3 mutations may serve as a potential biomarker for evaluating melanoma immunotherapy response." (PMID 34747716, 2021). "However, this study also noted an association between elevated NLRP3 gene expression scores and a positive prognosis in melanoma patients." (PMID 34638239, 2021). "Herein, we analyzed whether NLRP3 mutations were correlated with immunological and genomic features with publicly available data in melanoma." (PMID 34747716, 2021). "In the TCGA cohort, 89 (19.1%) of 467 melanoma patients harbored NLRP3 mutations." (PMID 34747716, 2021). "In melanoma, NLRP3 mutations were associated with better immunological and genomic characteristics." (PMID 34747716, 2021). "In addition to our published data, these results posit NLRP3 as a key driver of STAT3 in melanoma-associated inflammation." (PMID 34531850, 2021). "It has been demonstrated that both primary and metastatic melanoma cells possessed activated inflammasomes that was associated with co-expression of ASC and NLRP3, whereas self-dependence of melanoma cells on IL-1β signaling was shown to increase with the stage of disease." (PMID 32340261, 2020).
melanoma (continued). "In the second grade, IL-1R is expressed and in the third progressive stage the NLRP3 inflammasome is active constitutively, a correlation has been shown between the NLRP1 and NLRP3 variations and melanoma risk, with the greatest correlation between NLRP1 and nodular melanoma." (PMID 30447690, 2018). "Other groups have found that in NLRP3-/- mice, the number of tumor-associated MDSCs was significantly decreased, and the mice displayed a better response to dendritic cell vaccination against melanoma than wild-type mice." (PMID 28732079, 2017). "Notably, this analysis highlighted a strong correlation between NLRP3 expression and patient survival, especially in melanoma and hepatocellular carcinoma, where higher NLRP3 levels were linked to improved survival rates, a more favorable prognosis, and enhanced responses to immunotherapy." (PMID 40141358, 2025). "Despite these reports supporting the pro-tumorigenic role of the NLRP3 inflammasome, we should note that research has additionally indicated a tumor-protective role in certain cancers, such as colitis-associated cancer, colorectal cancer, hepatocellular carcinoma, and melanoma." (PMID 38397043, 2024). "Polymorphisms in the NLRP3 gene have been linked to the development of malignant melanoma, with an activation amplitude correlating with the stage of the disease; constitutive inflammasome activation is often found in late stages of melanoma, surrounded by elevated IL-1β level." (PMID 37891577, 2023). "In addition, some other research studies indicated that inflammasome NLRP3 could make IL-1β secretion increased and T cell responses suppressed, which were associated with tumor development in melanoma." (PMID 36276158, 2022). "Therefore, instead of choosing TMB and NB, NLRP3 mutations may be an alternative surrogate for predicting ICI response in melanoma." (PMID 34747716, 2021). "NLRP3 mutations may harbor vitally predictive implications for immunotherapy response in melanoma." (PMID 34747716, 2021). "Studies on melanoma cell lines suggest that sensitivity to the nigericin activator of NLRP3 was associated with high levels of NLRP3 complex proteins and other inflammasome sensors (unreported data) but whether levels are associated with different states of differentiation remains to be studied." (PMID 32027447, 2020). "In conclusion, Panx1/P2X7 is upstream of the NLRP3 inflammasome, but two different arms of its downstream signalling pathway could be either implicated in tumorigenesis in the case of melanomas, or cell death in the case of colon cancer cells that express LXRs." (PMID 27229305, 2016). "For instance, activation of NLRP3 in melanoma cells can lead to the release of HSP70, which stimulates the recruitment of PMN-MDSCs in lung epithelial cells." (PMID 38523155, 2024). "Following the activation of NLRP3 in melanoma cells, PMN-MDSCs proliferate in response to IL-1β-induced melanoma-associated inflammation, which results in reduced natural killer and CD8 + T cell activity and enhanced Treg cell population in primary tumors." (PMID 38609997, 2024). "For example, increased NLRP3 activity in melanoma due to immunotherapy has been shown to regulate the expressions of PD-L1 and Cd155 in the tumor microenvironment." (PMID 39769450, 2024). "Paradoxically, NLRP3 plays an immunosuppressive role in melanoma tumor cells by recruiting myeloid-derived suppressor cells (MDSCs)." (PMID 38229080, 2024). "Activation of NOD-like receptor protein 3 (NLRP3) and formation of the NLRP3 inflammasome in melanoma have been reported." (PMID 38609997, 2024). "Therapies that inhibit the NLRP3 inflammasome can block melanoma migration by suppressing the secretion of IL-1β and IL-18 cytokines and/or activating natural killer cells." (PMID 39275245, 2024). "NLRP3 and NLRP1 inflammasomes polymorphisms were associated with susceptibility to melanoma in a Swedish case-control study." (PMID 37020871, 2023).
melanoma (continued). "Constitutively activated NLRP3 in melanoma secretes IL-1β that initiates IL-6 secretion through stimulating IL-1R." (PMID 36932407, 2023). "Because IL-1β is secreted via various pathways, TQ as an inhibitor to NFκB and NLRP3 in melanoma was an excellent candidate to lessen its expression in the current study." (PMID 37762557, 2023). "NLRP3 is upregulated in a number of cancers, including head-and-neck, gastric, lung, kidney, melanoma, and myelodysplasia, and it often drives cancer progression and immunosuppression, correlating with poor patient outcomes." (PMID 37289257, 2023). "Considering the constitutive and high levels of NLRP3 and of IL-1α in melanoma, we investigated the effects of NLRP3 inhibition on STAT3 activity and its phosphorylation." (PMID 36672229, 2023). "Nevertheless, melanoma expresses high NLRP3-derived IL-1β expression, which specifically induces pSTAT3 and amplifies IL-6 secretion through the IL-1β/IL-6/STAT3 axis in vivo, leading to a further expansion of MDSCs." (PMID 36911674, 2023). "FMD can reduce pro-oxidative stress and NLRP3-derived inflammation in myocardial tissues of melanoma-bearing mice, indicating cardioprotective effects." (PMID 37684243, 2023). "In conclusion, our work shows evidence of extremely low NLRP3 expression and IL‐1β secretion by melanoma cells and highlight differences between CM and UM." (PMID 36707938, 2023). "Ablation of the NLRP3/pro-IL-1β inflammasome rewires MDSC function, promotes melanoma and breast cancer regression, and causes cisplatin resistance." (PMID 36911674, 2023). "In melanoma, macrophage-derived NLRP3/IL-1β pathway promotes migration and invasion of melanoma cells, which can be blocked through NLRP3 knockout, caspase-1 knockout, or NLRP3 inhibitor, celastrol." (PMID 36932407, 2023). "The biological importance of the NLRP3 inflammasome in many diseases, including colorectal cancer, melanoma and metastases, is dependent on its ability to respond to multiple signals." (PMID 37497237, 2023). "We observed that NLRP3 inhibition with the orally active OLT1177 significantly reduced tumor growth of B16F10 melanoma; other studies also report the anti-tumor property of OLT1177." (PMID 36672229, 2023). "One study examined its inhibitory impact on NLRP3 in human and mouse melanoma in vitro with increasing concentrations of TQ: 5, 10, and 20 μM for a fixed duration (24 h); TQ showed a dose-dependent inhibitory effect." (PMID 37762557, 2023). "Recent studies also reveal that tumor-specific NOD-like receptor protein 3 (NLRP3) is highly expressed and is active in melanoma." (PMID 36672229, 2023). "Diminished lung metastasis of melanoma cells was observed in NLRP3 knockout mice, with increased infiltration of activated NK cells and production of IFN-γ." (PMID 35990696, 2022). "Our data show that pharmacologic inhibition of inflammasome induces regression of melanoma growth and re-programs the MDSC compartment in a similar fashion to Nlrp3-deficient mice." (PMID 36032139, 2022). "In melanoma cells, NLRP3/IL-1β activation contributes to the expansion of MDSCs in the TME, thus reducing NK- and CD8+ T cell activity and increasing the Treg population." (PMID 36376979, 2022). "The percentage of MDSCs in melanoma, thymoma, and breast cancer in mice was decreased with NLRP3 deletion, but gemcitabine and 5-FU showed significantly increased antitumour efficacy and significantly prolonged survival." (PMID 35435776, 2022). "A phase III clinical trial (NCT03329846) is evaluating BMS-986299, a drug developed to activate NLRP3 inflammasome, in combination with Nivolumab in patients with advanced melanoma." (PMID 35517498, 2022). "In mice, the NLRP3 inflammasome, IL-1β, and IL-18 support melanoma growth, migration, and metastasis." (PMID 36293159, 2022). "For example, in melanoma, it has been shown that tumor-NLRP3 activation drives chronic inflammation, resulting in anti-tumor immunity dysfunction." (PMID 35631400, 2022).